IL5 (interleukin 5)
Diseases named in the same sentence as IL5 in open-access papers (continued):
Sharing a sentence is not in itself a finding about the gene and the disease.
eosinophilia (continued). "T cells also play a key role in eosinophilic disorders of the GI tract, as overexpression of interleukin 5 (IL-5) in CD2+ T cells is sufficient to produce eosinophilia in the esophagus and small intestine of transgenic mice." (PMID 39192974, 2024). "IL-5 promotes selective eosinophil egress from the bone marrow and induction of lung tissue eosinophilia in allergen-sensitized and -challenged mice." (PMID 40047886, 2024). "The authors also showed that by depleting IL-13-producing cells (which include ILC2s) in mdx at 4 weeks of age, IL-5 levels were decreased and muscle eosinophilia was diminished, suggesting that IL-13 is required for eosinophil infiltration." (PMID 38585275, 2024). "Most cases in Europe and North America are labeled with a chronic type 2 inflammatory response with tissue eosinophilia and significantly elevated levels of tissue expression of IL-5 and CLC." (PMID 38978039, 2024). "The pathogenesis of EF suggests an increase in IL-2, IL-5, IL-10, and interferon-γ, which leads to eosinophilia and overexpression of immunoglobulins." (PMID 39200350, 2024). "When activated by the alarmins or lipid mediators in vivo in mice, ILC2s can drive tissue eosinophilia independently of functional T cells, reflecting their potent productions of IL-5, IL-9, GM-CSF, IL-13, and, in some contexts, IL-4." (PMID 40047886, 2024). "Eosinophilia and elevated levels of immunoglobulin E (IgE) are often observed in advanced CTCLs due to the shift to a Th2 response, and IL-5 represents the principal regulator of eosinophilia." (PMID 38607023, 2024). "Interleukin-5 (IL-5) is the main cytokine responsible for the dramatic, T cell-dependent increase in eosinophils (eosinophilia) in blood and tissues during H. contortus infections in sheep." (PMID 38338687, 2024). "We observed a marked increase in eosinophils, consistent with previous reports of interleukin-5 (IL-5)-driven eosinophilia following microfilarial killing by IVM." (PMID 39680571, 2024). "Administration of the LGG strain in other studies led to a reduction in airway hyperresponsiveness (AHR) and eosinophilia, as well as a decrease in the concentrations of IL-5 and IL-13." (PMID 39796449, 2024). "In clinical practice, IL‐2 leads to an increase in IL‐5, a crucial growth, differentiation, and activating factor for eosinophils, which results in eosinophilia." (PMID 38087769, 2024). "Studies show that IL-5 expression in specific cells can induce massive eosinophilia and an increase in total white blood cells." (PMID 38951159, 2024). "Th2 cells produce cytokines such as IL-4, IL-5, and IL-13, which are pivotal in promoting IgE synthesis and subsequent histamine release (IL-4 and IL-13), eosinophilia (IL-5), and mucus oversecretion, airway hyperresponsiveness, and remodeling (IL-13)." (PMID 39770422, 2024). "We reported that in vivo IL-5 gene delivery induces eosinophilia and enhances the expression of TGF-β, whose signal is transduced to other cells." (PMID 38785953, 2024). "Reducing glucose tolerance and body weight in a mouse model of T2D, likely mediated by the increase of eosinophilia and IL-5 in peripheral tissues." (PMID 39314046, 2024). "In the GSE36830 dataset, it is stated that polyp tissues from CRSwNP patients have significantly increased expression of ECP, IL-5, IL-13, and Eotaxin-1, 2, and 3 compared to normal tissues, indicating eosinophilia." (PMID 38975344, 2024). "Our data are consistent with this, as IAV-induced lung eosinophilia and the elevated secretion of the Th2 cytokine IL-5 were observed in TLR7 KO." (PMID 39769461, 2024). "New IL-5(R) antibodies mitigate morbidity and, consequently also mortality in cases of secondary and idiopathic eosinophilia." (PMID 39037514, 2024). "Blockage of IL-5 signaling by anti-IL-5 antibodies or IL-5 depletion reduced lung eosinophilia in animal models, suggesting a crucial role of IL-5 in eosinophilia." (PMID 38493955, 2024).
eosinophilia (continued). "We also observed a reduction in IL-5 and IL-13-expressingILC2s and T effector cells, whichwas associated with decreased BAL and lung eosinophilia, and reductions in type 2-polarizedCD11b+ DCs and M2 macrophages." (PMID 38935708, 2024). "Transgenic mice that over-express IL-5 display constitutive eosinophilia and are highly resistant to infection with N. brasiliensis." (PMID 39628481, 2024). "In conclusion, both persistent serum eosinophilia and atopy are associated with more severe phenotypes of AA, but future multiomics studies should establish if EoAA may represent a distinctive clinical endotype meritful of targeted therapeutic approach (i.e., IL-5 antagonists)." (PMID 39282571, 2024). "In mouse models, mothers with elevated IL‐5 mediate a foetal eosinophilia, resulting in pups with increased airway hyperreactivity and persistent airway epithelial nerve density into adulthood." (PMID 39323541, 2024). "IL-5 plays a critical role in maturation, activation and migration of eosinophils to the airways, which is also a major stimulator of eosinophilia in other Th2-driven diseases." (PMID 39717777, 2024). "IL‐5 is involved in airway eosinophilia and contribute to the development of bronchial hyperreactivity in ovalbumin challenged guinea pigs." (PMID 39245804, 2024). "It has been assessed that IL-5 plays a crucial role in the development of eosinophilia in Hodgkin’s lymphoma." (PMID 38607023, 2024). "Following this, we have investigated the effects of hyper-eosinophilia on muscle repair in acute damage conditions by using the IL5-Tg mice." (PMID 38585275, 2024). "Multiple lines of evidence suggest that VLS stems primarily from the systemic release of IL-5 and induction of eosinophilia." (PMID 39320047, 2024). "Our patients with SBA and relapsing CRSwNP who were candidates for adjunctive anti-IL-5 therapy exhibited persistent eosinophilia." (PMID 38337448, 2024). "At an early stage of tumour growth (∼150 mm3), eosinophilia was induced with cytokines IL-5 and/or IL-3329,48." (PMID 39471751, 2024). "The occurrence of eosinophilia in PCM patients is related to the high production of IL-5 due to the activation of the Th2 subpopulation, and has been reported mainly in the acute/subacute form." (PMID 38786672, 2024). "The two measures that seemed to have a statistically significant influence on long-term recurrence were eosinophilia-positive infiltrate (p <0.05) and IL-5 expression (p <0.05)." (PMID 39328679, 2024). "Adoptive transfer experiments with cells isolated from homozygous Red5 mice (Il5−/− mice), instead of Il5+/+ mice, revealed that the effects of ILC2s exhibiting the ILC9 phenotype on airway eosinophilia were entirely dependent on their own production of IL-5." (PMID 38597952, 2024). "Treatments that target eosinophilia, such as Mepolizumab (anti-human IL-5 monoclonal antibody), have positive effects in CF patients with T2 inflammation." (PMID 36849900, 2023). "Eosinophilia seems to play an important role in the pathogenesis of EF through elevated levels of eosinophilic cationic protein and serum interleukin-5 (IL-5) and increased eosinophilic migration capacity." (PMID 36768300, 2023). "IL-5 represents the key driver of eosinophilia, while the Il-4/IL-13 inflammatory pathway is strongly associated with FeNO, which, in turn, correlates with eosinophilic inflammation in the airways." (PMID 37947596, 2023). "CD4+ T cells show Th2 skewing and production of IL-4, IL-5, IL-13, contributing to the atopic phenotype seen in these patients of eczema and eosinophilia." (PMID 37727514, 2023). "Alarmins such as thymic stromal lymphopoietin (TSLP), IL-25 (IL-17E), and IL-33 stimulate type 2 ILC secretion of IL-5 to create eosinophilia." (PMID 37587450, 2023). "Several clinical trials have been completed or are ongoing with anti-IL5 biologicals in patients with secondary eosinophilia, such as eosinophilic asthma, eosinophilic esophagitis, and EGPA." (PMID 37274287, 2023).
eosinophilia (continued). "The eosinophils-deficient IL-5 gene-deficient mice and GATA1 gene-deficient mice, both develop tissue eosinophilia following disease induction in experimental models." (PMID 37524769, 2023). "The increased secretion of type-2 cytokines, such as IL-5, probably contributes to the eosinophilia and the higher titres of systemic IgE." (PMID 37696941, 2023). "TSLP, IL-5, IL-13 and IL-25 are the major proinflammatory cytokines that mediate eosinophilia-dominated type-2 inflammation." (PMID 37377967, 2023). "More robust results in patients treated with anti-IL5 biologicals or other targeted treatments, in primary or secondary eosinophilia, lowering the eosinophil count durably and maximally as well as research in this field is warranted." (PMID 37274287, 2023). "In fact, IL-5-transgenic mice, wherein IL-5 is overproduced by thymocytes and T cells, show massive eosinophilia." (PMID 37762936, 2023). "In contrast, untreated mice and those treated at day 7 after infection showed lower Th1 responses and robust Th2 responses (IL-5- and IL-13-producing T cells and increased eosinophilia)." (PMID 36719231, 2023). "Previous studies have shown that ovariectomy inhibits lung eosinophilia and IL-5 levels in the lung when exposed to ovalbumin (OVA)." (PMID 37664635, 2023). "Different IEI can manifest with elevated serum IgE or eosinophilia and increased Th-2 cytokine production, such as IL-5, which is an essential promoter of eosinophil differentiation, maturation, and survival." (PMID 36675441, 2023). "IL-5 promotes eosinophilia, and IL-4 and IL-13 enhance the production of eosinophil chemoattractants (CCL11/eotaxin-1, CCL24/eotaxin-2, and CCL26/eotaxin-3) and activate B cells, macrophages, fibroblasts, epithelial cells, and goblet cells." (PMID 37674852, 2023). "In white patients, 80%–90% of nasal polyps (NPs) are characterized by prominent eosinophilia with high amounts of IL-5." (PMID 38143494, 2023). "ILC2s and a subpopulation of CD4+ T cells known as Th2 cells can secrete IL-4, IL-5, and IL-13 and stimulate type 2 immunity with high IgE antibodies and eosinophilia." (PMID 37152304, 2023). "The knowledge of molecular pathways sustaining the production of IL-5 and, consequently, of eosinophilia in respiratory disease is essential information to choose the most effective biological treatment for each patient." (PMID 37108417, 2023). "These cells are responsible forinterleukin (IL) 4, IL-5, IL-9, and IL-13 as well asabnormal immunoglobulin production, i.e., atopy,eosinophilia, and mast cell enlargement." (PMID 37345397, 2023). "CRSwNP patients characterized by eosinophilic inflammation and type 2 inflammation have high levels of immunoglobulin (Ig) E, interleukin (IL‐5), IL‐4 and IL‐13 in local tissues, often accompanied by eosinophilia in peripheral blood." (PMID 36840493, 2023). "For instance, Interleukin-5 (IL-5) is essential for airway eosinophilia, and Interleukin-4 (IL-4) and Interleukin-13 (IL-13) are necessary for Immunoglobulin E (IgE) production." (PMID 37781715, 2023). "The eosinophilia observed has been described previously and is likely due to the release of IL-5 and GM-CSF release by IL-2-stimulated CD4-positive lymphocytes." (PMID 36765608, 2023). "High levels of IL-5 are commonly observed in intestinal helminth- and protozoa-infected hosts, and it also induces eosinophilia, another common manifestation of parasite infection." (PMID 37513018, 2023). "Type 2 inflammation is a pattern of immune response involving a subpopulation of CD4+ T cells known as Th2 cells that secrete IL-4, IL-5, and IL-13 and stimulate Type 2 immunity, which is characterized by high IgE antibody titers and eosinophilia." (PMID 37614956, 2023). "In patients with eosinophilia, the presence of IL-17 and IL-5 in combination act synergistically to enhance eosinophilic cytolytic activity." (PMID 37614956, 2023).
eosinophilia (continued). "Reversing this effect with exogenous IL-5 treatment induces eosinophilia and suppresses metastasized melanoma cells’ expansion and proliferation." (PMID 37587450, 2023). "Serum IL-5 and total IgE concentrations were parallel with peripheral blood eosinophilia and clinical symptoms, and related with disease activity." (PMID 36732834, 2023). "In the T2 endotype, there is an increase in the production of Th2 cytokines, including interleukin-4, interleukin-5, and interleukin-13, high levels of immunoglobulin-E in polyp tissue, and eosinophilia." (PMID 37674852, 2023). "In IL‐5 transgenic mice, overexpression of IL‐5, which leads to a high population of functional eosinophils (eosinophilia), enhanced filarial parasite killing." (PMID 37283884, 2023). "It reduces pulmonary responses to antigen, tissue eosinophilia and IL-5 expression in inflammatory cells and decreases elevated levels of IL-1β and IL8 in viral upper respiratory tract infections." (PMID 35359601, 2022). "Using a mouse model of IL-2–anti-IL-2 antibody complex injection, the Bluestone group demonstrated that ILC2 cells were the primary IL-5–expressing cells arising following these injections, and that ablation of all IL-5+ cells prevented eosinophilia." (PMID 35699942, 2022). "Th2 cytokines, such as IL-4, IL-5, and IL-13, directly or indirectly promote eosinophilia by influencing eosinophil differentiation, survival, and activation." (PMID 36362100, 2022). "While neutrophilia was promoted, depletion of ACh also prevented the characteristic eosinophilia associated with Alternaria exposure, most likely due to restricted ILC2 activation and release of IL-13 and IL-5." (PMID 35711456, 2022). "Neutralization of IL-5 in Cd19CreRosaIL-2 mice prevented the eosinophilia, demonstrating that B cell–specific production of IL-2 initiated an unconventional cellular circuit expanding IL-5–expressing ILC2s and, downstream, eosinophils." (PMID 35699942, 2022). "Intranasal administration of Hp‐TGM during Alternaria exposure sharply reduced airway and lung tissue eosinophilia along with bronchoalveolar lavage fluid IL‐5 and lung IL‐33 cytokine levels at 24 h." (PMID 35758054, 2022). "In contrast to our findings, the authors found an increase in melanoma bone marrow metastasis utilizing a similar transgenic mouse model of IL-5-driven eosinophilia." (PMID 35756626, 2022). "Polyp tissues identified with eosinophilia revealed a co-localization of ILC2s and eosinophils, indicating a possible cross-talk between IL-5-producing ILC2s and IL-4-producing eosinophils to support reciprocal activation and survival." (PMID 35359972, 2022). "Polyps showing eosinophilia with an increased Th2 response (e.g., increase of IL-4 and IL-5 levels) is the dominant inflammatory endotype in Caucasian patients, while a high proportion of neutrophilic polyps is found in Asian patients." (PMID 35720287, 2022). "IL-5 elevation can induce eosinophilia in circulating blood or tissues by triggering eosinophil production and preventing eosinophil destruction." (PMID 35707392, 2022). "In the first clinical trials, in the 1980s, of recombinant human IL-2 in primary immunodeficiency, AIDS, and cancer, patients almost invariably developed eosinophilia, accompanied by high IL-5 titers." (PMID 35699942, 2022). "Subsequent clinical trials have confirmed the strong predictive value of sputum eosinophilia for anti-IL5 responsiveness." (PMID 36237537, 2022). "The Th2-predominant response favored humoral response and also promoted tissue/peripheral eosinophilia in NEMOΔCol1a2 mice, as IL5 is a known potent mediator for eosinophil activation and maturation." (PMID 35624133, 2022). "Specifically, anti-IL-5 (mepolizumab, reslizumab), anti-IL-5 receptor α (benralizumab), and prostaglandin D2 receptor antagonist (fevipiprant) reduce sputum eosinophilia, and the efficacy of IL-4 receptor (dupilumab) has already been proven." (PMID 35887589, 2022).
eosinophilia (continued). "In accordance, anti-IL-5 antibody treatment, suppressed tissue eosinophilia and prevented the protection." (PMID 36389745, 2022). "ILC2s boost airway eosinophilia via IL-5 production and enhance AHR, goblet cell hyperplasia and Th2-mediated AAI through IL-13 secretion." (PMID 36305904, 2022). "Infection with N. brasiliensis induces adipose eosinophilia and enhances glucose tolerance in mice fed a high fat diet via activation of AT ILC2s, which induces IL-5 production that leads to accumulation of eosinophils in the AT." (PMID 35625566, 2022). "On the other hand, BALB/C mice develop a predominant Th2 response, producing IL-4, IL-5, IL-6, favoring IgE production and eosinophilia." (PMID 36263051, 2022). "Th1 cells drive a predominant cellular cytotoxic immunity mediated by IL-12/IFN-γ, whereas Th2 cells facilitate IL-4/IL-5-mediated humoral responses, notably through immunoglobulin E (IgE) production and eosinophilia." (PMID 36263051, 2022). "CCL8 has been shown to be central to recruiting IL-5 producing Th2 cells, which in turn regulate eosinophilia, thus linking these transcript changes to the hallmarks of DRESS." (PMID 35703984, 2022). "For example, ILC2s are enriched in nasal polyps of chronic rhinosinusitis patients along with elevated IL5 and IL13 transcripts, suggesting an ILC2-dependent contribution to the disease-associated eosinophilia and chronic airway inflammation." (PMID 35359972, 2022). "First, blood eosinophil counts were found to be poorly correlated with sputum eosinophils in patients on chronic systemic corticosteroids, leading to the underestimation of eosinophilia (and likely underuse of anti-IL5 therapy) in these patients." (PMID 36237537, 2022). "We demonstrated in an earlier study that the airway eosinophilia in allergen-specific T cell-transferred mice was abrogated by anti-IL-5 neutralizing antibody treatment." (PMID 36422599, 2022). "The eosinophilia and atopic dermatitis in our patients are suggestive of increased Th2 function via elevated production of IL-5 and IL-4, respectively." (PMID 36605204, 2022). "Here, L. lactis‐EVs significantly reduced eosinophilia (IL‐5‐mediated) and mucus production (IL‐13‐mediated) in allergic asthmatic mice by enhancing Th1 immune response." (PMID 35344296, 2022). "These cells produced large amounts of IL-5 and IL-13 and induced early eosinophilia in the lung when encountering the second nematode." (PMID 36466877, 2022). "T-bet deficiency thus underlies the excessive production of Th2 cytokines, particularly IL-5 and IL-13, by CD4+ αβ T cells, causing blood eosinophilia and UAI." (PMID 35909394, 2022). "FeNO generally correlates with airway eosinophilia, but the degree of correlation is insufficient for it to be useful in predicting the efficacy of anti-IL5 therapy." (PMID 36237537, 2022). "Type 2 is characterized by upregulated production of the cytokines IL-4, IL-5, and IL-13, local IgE and profound eosinophilia." (PMID 36291990, 2022). "The IL-5 and IL-13 Th2 cytokines present in the tumor microenvironment of SS patients also favor eosinophilia, and IL-4 increases IgE." (PMID 35055124, 2022). "In atopic asthmatic patients, a placebo-controlled trial showed that the inhaled GATA-3-specific DNAzyme SB010 successfully attenuated allergen-induced sputum eosinophilia, and also decreased plasma levels of IL-5." (PMID 36140282, 2022). "In contrast, depletion of ACh inhibited Alternaria-induced activation of ILC2s, suppressing the expression of IL-5, IL-13, and subsequent eosinophilia." (PMID 35711456, 2022). "Th2 cytokines such as IL-4, IL-13, and IL-9 promote eosinophilia by regulating local IL-5, eotaxin synthesis, and/or inhibiting IFN-gamma production." (PMID 35805534, 2022). "ILC2s produce large amounts of IL-5 and IL-13 in response to activation with IL-33, resulting in eosinophilia and this has been adopted as a robust model for innate induction of airway inflammation." (PMID 35711456, 2022).